LAMP1 (lysosome associated membrane protein 1)
Diseases named in the same sentence as LAMP1 in open-access papers (continued):
Sharing a sentence is not in itself a finding about the gene and the disease.
diffuse large B-cell lymphoma (1 paper, 2024). "In diffuse large B-cell lymphoma (DLBCL), the combination of patient LAMP1 expression and survival data demonstrated a correlation between high LAMP1 expression and poor prognosis." (PMID 39669571, 2024).
emphysema (1 paper, 2022). "Furthermore, we found a significantly higher co-localization of TOM20 with lysosome degradation marker LAMP1 in ATII cells in emphysema compared to control organ donors." (PMID 35884802, 2022).
encephalitis (1 paper, 2022). An acute inflammatory process affecting the brain parenchyma. "The level of LAMP-1 in the CSF of patients with anti-NMDAR encephalitis was also significantly different from that of the controls, and it has been found to be involved in the autophagy process." (PMID 36389787, 2022). "In our study, cytokine array analysis results showed the downregulation of LAMP-1 levels in the CSF of patients with anti-NMDAR encephalitis." (PMID 36389787, 2022). "As shown in the volcano plot, among these three differentially expressed cytokines and inflammatory mediators, cIAP-1 and MCSF showed higher levels in CSF of anti-NMDAR encephalitis patients than of controls, while LAMP-1 had lower level in anti-NMDAR encephalitis patients." (PMID 36389787, 2022). "Given few reports of its expression at this disease, the mechanism of LAMP-1 in anti-NMDAR encephalitis remains unclear and it needs to be paid more attention in future research." (PMID 36389787, 2022). "The LAMP-1 in CSF of anti-NMDAR encephalitis patients was higher than that of the control group, but that from the anti-NMDAR encephalitis group and the viral encephalitis group was not statistically different." (PMID 36389787, 2022).
endothelial dysfunction (1 paper, 2025). In vascular diseases, endothelial dysfunction is a systemic pathological state of the endothelium (the inner lining of blood vessels) and can be broadly defined as an imbalance between vasodilating and vasoconstricting substances produced by (or acting on) the endothelium. "Our data showed that LAMP1 displayed an increasing trend both in vitro and in vivo in the endothelial dysfunction model, which was consistent with that of LC3II/I and P62 levels, suggesting a potential connection with the buildup of autolysosomes." (PMID 40098620, 2025).
esophageal adenocarcinoma (1 paper, 2020). A malignant tumor with glandular differentiation arising predominantly from Barrett mucosa in the lower third of the esophagus. "Noteworthy, AXL has been shown recently to mediate the anterograde trafficking of lysosomes (Lamp1-positive vesicles) in esophageal adenocarcinoma cells, regulating the secretion of cathepsin B, which is involved in matrix degradation and invasion." (PMID 31963783, 2020).
esophageal cancer (1 paper, 2022). A primary or metastatic malignant neoplasm involving the esophagus. "Moreover, EVs isolated from esophageal cancer (ECA) cells carrying lysosomal associated membrane protein 1 (LAMP1) and MMP-9 induced naive B cells to differentiate into TGF-β-producing regulatory B cells, which led to immunosuppressive effects on CD8+ T-cells." (PMID 35493080, 2022).
Fabry disease (1 paper, 2014). Fabry disease (FD) is a progressive, inherited, multisystemic lysosomal storage disease characterized by specific neurological, cutaneous, renal, cardiovascular, cochleo-vestibular and cerebrovascular manifestations. "Although Fabry disease is considered first and foremost a vasculopathy by many investigators, our findings also demonstrate increases in parenchymal LC3 and LAMP-1 immunoreactivity localized to perinuclear and neuritic regions of neurons." (PMID 24529306, 2014).
familial amyotrophic lateral sclerosis (1 paper, 2021). An instance of amyotrophic lateral sclerosis that is caused by an inherited modification of the individual's genome. "It was previously shown that LAMP1 intensity did not represent degradative lysosomes or autolysosomes under physiological and pathological conditions in familial amyotrophic lateral sclerosis-linked motor neurons." (PMID 34147843, 2021).
fucosidosis (1 paper, 2015). "Measures strongly associated with substrate accumulation including cerebrocortical vacuolation, ‘vacuoles per neuron’, perivascular accumulation and LAMP-1 gene expression demonstrated significant reductions in fucosidosis dogs treated with intracisternal ERT." (PMID 26537923, 2015).
fungal infection (1 paper, 2023). "After A549 cell fungal infection, cell lysis, and ultracentrifugation, 13 fractions of 1 mL each were collected, submitted to Western blot, and the presence or not of α3 integrin, the early endosome marker EEA1, and the late endosome/lysosome marker LAMP-1 was analyzed." (PMID 37755020, 2023).
gastric adenocarcinoma (1 paper, 2023). "We previously established that the vacuolating toxin (VacA) secreted by Helicobacter pylori (Hp) impairs TRPML1 activity and induces cell vacuolation in AGS (gastric adenocarcinoma) cells, as assessed by Lamp1 (lysosomal-associated membrane protein 1) immunolabelling 41–43." (PMID 40395298, 2023).
gastrointestinal stromal tumor (1 paper, 2020). "We noted a diffuse distribution of LAMP1 in patient tumor samples with Gastrointestinal stromal tumor (GIST) and Merkel cell cancers with PDGF mutations using immunohistochemistry of LAMP1." (PMID 32194831, 2020).
Gliosis (1 paper, 2016). Gliosis is the focal proliferation of glial cells in the central nervous system. "It should be noted that the increased LAMP1 levels could be attributable to gliosis in the tauopathy patients." (PMID 26936765, 2016).
heart failure (1 paper, 2025). Inability of the heart to pump blood at an adequate rate to meet tissue metabolic requirements. "Lysosomal‐associated membrane protein 1 (LAMP1) plays a crucial role in autophagy, a process that is activated in pathological conditions such as heart failure and the diabetic heart." (PMID 40296367, 2025).
hereditary spastic paraplegia (1 paper, 2025). Hereditary spastic paraplegias (HSP) comprise a genetically and clinically heterogeneous group of neurodegenerative disorders characterized by progressive spasticity and hyperreflexia of the lower limbs. "Interestingly, the enlargements of LAMP1-positive structures had been reported in hereditary spastic paraplegia and other neurodegeneration diseases." (PMID 39823474, 2025).
homocystinuria (1 paper, 2016). An autosomal recessive inherited metabolic disorder caused by mutations in the CBS, MTHFR, MTR, and MTRR genes. "Because changes in cell death by autophagy merit further investigation with respect to homocystinuria, we analysed protein levels of a specific autophagy marker: LAMP1 (lysosomal-associated membrane protein 1), as well as autophagosome formation in live cells." (PMID 26959487, 2016).
idiopathic pulmonary fibrosis (1 paper, 2025). Idiopathic pulmonary fibrosis (IPF) is a nonneoplastic pulmonary disease that is characterized by the formation of scar tissue within the lungs in the absence of any known cause. "Notably, pathways related to pulmonary fibrosis, such as TGF‐β regulation, extracellular matrix organization, or collagen biosynthesis, were preferentially upregulated in Lamp1‐enriched cells from the BLM‐treated mice." (PMID 40545776, 2025).
injury (1 paper, 2021). Damage inflicted on the body as the direct or indirect result of an external force, with or without disruption of structural continuity. "Knockout of PGRN promotes the upregulation of lysosome-related genes such as lysosomal-associated membrane protein 1 (Lamp1) induced by traumatic brain injury." (PMID 34072424, 2021).
laryngeal squamous cell carcinoma (1 paper, 2024). A squamous cell carcinoma that arises from the larynx. "In laryngeal squamous cell carcinoma (LSCC), LAMP1 expression levels are elevated in comparison to normal tissues, showing statistically significant associations with lymph node metastasis and TNM staging." (PMID 39669571, 2024).
lentivirus infection (1 paper, 2017). Virus diseases caused by the Lentivirus genus. "To investigate membrane rupture, we introduced mCherry fused to N-terminus of Galectin-3 (mCherry-Galectin-3) into H4/V1S-SV2/LAMP1-eCFP cells via lentivirus infection." (PMID 28794446, 2017).
MELAS (1 paper, 2024). "This is consistent with our findings of increased LAMP1 expression in muscle samples from m.3243 A > G MELAS patients." (PMID 38741129, 2024). "Since muscle samples from m.3243 A > G MELAS patients contain a large amount of RRF, the increased level of LAMP1 observed in the muscles of MELAS patients may be related to the increased number of lysosomes in RRF." (PMID 38741129, 2024). "In the muscles of m.3243 A > G MELAS patients, protein expression of LAMP1 was increased rather than decreased." (PMID 38741129, 2024). "In contrast, there were no significant changes in LAMP1, SQSTM1 and LC3B-II protein levels in skin fibroblasts from m.3243 A > G MELAS patients." (PMID 38741129, 2024).
metastatic cancer (1 paper, 2022). A carcinoma which has spread from the original site of growth to another anatomic site. "The presence of LAMP1 on the surface of cells may play a role in the migratory or invasive functions of these cells, including those of metastatic cancer cells and immune response cells." (PMID 35563467, 2022).
myopia (1 paper, 2022). "This specific distribution could lead to our current conclusion that low initial myopia would have an excellent response to 0.01% atropine treatment, contradicting the results of the ATOM1 and LAMP1 studies with higher myopia at baseline than ours." (PMID 35513480, 2022).
Niemann-Pick disease, type C1 (1 paper, 2022). Type C Niemann-Pick disease associated with a mutation in the gene NPC1, encoding Niemann-Pick C1 protein. "We suspect that the larger LAMP1 species (120 kDa) may be caused by hyper-glycosylation, as previously observed in in brain of Niemann-Pick disease type C1 (NPC1) from mouse models and patients." (PMID 36113749, 2022).
oncocytomas (1 paper, 2020). "Two proteins—LAMP1 and ITGAV—were selected for verification in an independent cohort of oncocytomas and chRCC, with ITGAV1 expression to exhibit strong staining in oncocytomas, whereas LAMP1 staining was robustly detected in chRCC." (PMID 32742246, 2020).
oral squamous cell carcinoma (1 paper, 2022). "Nonetheless, the expression of LAMP1 in oral squamous cell carcinoma (OSCC) has not been investigated yet." (PMID 35145930, 2022). "The obtained results pointed to the overexpression of LAMP1 in OSCC, as well as its correlation with tumor grade and metastasis; therefore, LAMP1 might have a role to play in OSCC pathogenesis and could be regarded as an independent prognostic marker in oral squamous cell carcinoma." (PMID 35145930, 2022).
poliovirus infection (1 paper, 2020). An disease or disorder caused by infection with Enterovirus C. "Similar to EV71 and CVB3, poliovirus infection was found to recruit LC3 to the viral replication complex, which was also co-localized with LAMP1 (autolysosome/lysosome marker)." (PMID 32674313, 2020).
retinal degeneration (1 paper, 2020). Degeneration of the retina. "Enigmatically, LAMP‐1 expression was markedly—andrepeatedly—elevated in the CD20 compartment of the CLN3‐associated retinal degeneration patient." (PMID 32685355, 2020). "LAMP‐1 expression did not change over time: expression of LAMP‐1 was stable in all lymphocyte compartments (P = .53 for CD4, P = .11 for CD8, P = .14 for the CD20 without the CLN3‐associated retinal degeneration subtype)." (PMID 32685355, 2020).
rheumatoid arthritis (1 paper, 2024). A chronic, systemic autoimmune disorder characterized by inflammation in the synovial membranes and articular surfaces. "Furthermore, peripheral blood mononuclear cells (PBMCs) from patients with rheumatoid arthritis (RA) show increased RNF13 levels and decreased LAMP‐1 expression." (PMID 39031743, 2024).
Sandhoff disease (1 paper, 2021). A lysosomal disorder from the GM2 gangliosidosis family, caused by biallelic pathogenic variants in the HEXB gene, characterized by GM2 ganglioside accumulation in the nervous system and progressive central nervous system degeneration. "A significant increase in HexA co-localisation with LAMP-1 was observed alongside the elevated expression of the mature form of HexA -findings shared between Tay–Sachs and Sandhoff diseases." (PMID 34831346, 2021).
sarcopenia (1 paper, 2021). Progressive decline in muscle mass due to aging which results in decreased functional capacity of muscles. "During the course of sarcopenia progression in SAMP8 mice, elevated Atg13 and LC3-II levels were associated with the accumulation of p62 and lysosome-associated membrane protein 1 (LAMP1), suggesting that poor fusion between autophagosomes and lysosomes and impaired mitophagy in sarcopenic mice." (PMID 34881083, 2021).
T-cell lymphoma (1 paper, 2025). "Additionally, DDR2 regulates T-cell lymphoma apoptosis via the miR-615-5P/DDR2 pathway in lysosomal-associated membrane protein 1 (Circ-LAMP1) modulation." (PMID 40563472, 2025).
tauopathies (1 paper, 2016). "Our analysis of lysosomal markers showed increased protein levels of LAMP1 and Cat D in FAD patients as well as in patients with primary tauopathies, suggesting a defective lysosomal clearance which is in line with previous reports in AD brain." (PMID 26936765, 2016). "Increased levels of the lysosomal marker LAMP1 was detected in FAD and CBD, and in addition Cathepsin D was diffusely spread in the cytoplasm in all tauopathies suggesting an impaired lysosomal integrity." (PMID 26936765, 2016).
trisomy 21 (1 paper, 2021). A chromosomal disorder consisting of the presence of an extra chromosome 21. "Of note, the average size of LAMP1 + vesicles in fixed cells with trisomy 21 was smaller." (PMID 34040082, 2021). "In cells with and without trisomy 21, the extent of colocalization of FcRn with the endosomal marker EEA1 was ~ 40% (PCC DS: 0.40 ± 0.10, PCC NDS: 0.43 ± 0.12), and the extent of colocalization of FcRn with LAMP1 was ~ 10% (PCC DS: 0.10 ± 0.05, PCC NDS: 0.09 ± 0.03)." (PMID 34040082, 2021).
type 1 diabetes (1 paper, 2021). "We also observed reduced colocalisation of proinsulin with LAMP1 in donors with type 1 diabetes (p < 0.001)." (PMID 33515072, 2021).
tumor (505 papers, 2007 to 2026). "Despite the established association of LAMP1 with tumor biology, the precise mechanisms by which LAMP1 influences tumor progression, metastasis, and treatment resistance remain inadequately understood." (PMID 40872517, 2025). "Lysosomal-associated membrane proteins (LAMPs), particularly LAMP1, have attracted significant attention for their involvement in tumor progression." (PMID 40872517, 2025). "Specifically, we investigated cytolytic degranulation after tumor encounter by measuring the cumulative surface expression of the lysosomal-associated membrane protein 1 (LAMP-1; CD107a)." (PMID 39792660, 2025). "Lysomembrane-associated protein 1 (LAMP1), known to exhibit differential expression in various tumor types and play a crucial role in the development of tumors." (PMID 39669571, 2024). "Using the median value of LAMP1 expression as a cut-off, we found that high expression of LAMP1 was associated with N and M stage and tumor stage, as also demonstrated for hsa_circRNA101303." (PMID 38824581, 2024). "To trace the fate of neutrophils in tumor cells after internalization, we used lysosomal-associated membrane protein 1 (LAMP1) as a marker for lysosomes." (PMID 38806658, 2024). "We designed a cancer vaccine utilizing our nucleic acid platform, UNITETM (UNiversal Intracellular Targeted Expression), which fuses a tumor-associated antigen with lysosomal-associated membrane protein 1 (LAMP1)." (PMID 37711623, 2023). "A previous study on the immunohistochemical expression of LAMP1 in ESCC suggested that the LAMP1expression was significantly associated with degrees of tumor histological differentiation." (PMID 35145930, 2022). "As evidenced by the results of the present study, the expression of LAMP1 was associated with tumor histological differentiation and metastasis." (PMID 35145930, 2022). "For cell apoptosis and invasion assay, knockdown of miR‐556‐5p or miR‐567 evidently rescued the tumour suppressor function caused by si‐circ‐LAMP1‐1 in KMBC cells." (PMID 33675150, 2021). "In the current work, we investigated its clinical significance and found the patients with high expression of circ‐LAMP1 was linked to more than one tumour, and higher TNM stages." (PMID 33675150, 2021). "In normal cells, LAMP-1 is normally expressed in lysosomes, though it is transferred to the surface of tumor cells, where its expression level is associated with invasion and metastasis of different types of tumors." (PMID 33724757, 2021). "LAMP1 is a lysosome‐associated membrane protein which has been implicated in several tumor‐promoting activities such as promotion of metastasis, drug resistance, and cancer cell survival." (PMID 31784980, 2020). "Among eleven representative genes showing high correlations between copy number and gene expression in this study, LAMP1 is a late endosomal/lysosomal marker associated with tumor cell motility and invasiveness." (PMID 26863628, 2016). "GzmB was restrained in the granules of internalized NK92 at the early time point (2 h), as GzmB was colocalized with lysosomal-associated membrane protein 1 (LAMP1) in internalized NK92 cells after entering MCF7 tumor cells (upper row)." (PMID 24113190, 2013). "This suggests a role for LAMP1 in pathways associated with tumor progression." (PMID 40872517, 2025). "In addition to their essential role in maintaining lysosomal function, LAMP1 is also implicated in autophagy regulation as well as tumor cell metastasis and invasion, thereby influencing tumor progression." (PMID 39669571, 2024). "LAMP1 expression has been implicated in prognosis across various tumor types." (PMID 39669571, 2024). "It is plausible that LAMP1 may be associated with tumor autophagy and VHL gene regulation; nevertheless, its specific mode of action in ccRCC remains elusive." (PMID 39669571, 2024).